IFITM10 (interferon induced transmembrane protein 10)
Synonyms: DSPA3
Tractability: Antibody: UniProt places it where antibodies can reach, with medium confidence; UniProt predicts a signal peptide or a membrane-spanning region; its Gene Ontology location is reachable by antibodies, with medium confidence.
Gene: Protein-coding gene on chromosome 11 (1,732,406 to 1,750,605, reverse strand). Ensembl gene ENSG00000244242.
Subcellular location: Cell membrane
Gene Ontology:
Cellular component: plasma membrane; membrane
Genetic constraint (gnomAD): Loss-of-function variants: 17 observed, 16.99 expected, observed/expected ratio (o/e) 1, 90% interval 0.68 to 1.5. The upper end of that interval is the gene's LOEUF score, 1.5, which puts it in group 6 of 6, group 1 being the genes least tolerant of losing a copy. Missense variants: 306 observed, 291.31 expected, observed/expected ratio (o/e) 1.05, 90% interval 0.96 to 1.15. Synonymous variants: 148 observed, 136.85 expected, observed/expected ratio (o/e) 1.08, 90% interval 0.94 to 1.24.
Homologues: Orthologues: rat Ifitm10 (87% identical), guinea pig IFITM10 (85% identical), mouse Ifitm10 (84% identical), pig IFITM10 (82% identical), tropical clawed frog ifitm10 (39% identical), zebrafish ifitm1 (15% identical). Paralogues in human: IFITM3 (21% identical), IFITM2 (20% identical), IFITM1 (19% identical), IFITM5 (14% identical).
Diseases named in the same sentence as IFITM10 in open-access papers:
IFITM10 is named in the same sentence as 17 diseases in open-access papers, as found by Europe PMC text mining. Sharing a sentence is not in itself a finding about the gene and the disease. The quoted sentences say what the papers report.
COVID-19 (2 papers, 2021). A disease caused by infection with severe acute respiratory syndrome coronavirus 2. "We demonstrated the downregulation of IFITM10, CH25H, NCR3, and KLRK1 and the upregulation of ID1 in the PBMCs from RTP patients compared with that from patients with moderate or severe COVID-19." (PMID 34687295, 2021). "Eight ISGs were downregulated in Asymptomatic as compared with severe COVID-19 cases; CNP, CSF1, IRF1, IFITM10, IRF2BP2, IRF2BPL, SLC25A28 and SOCS3." (PMID 34824360, 2021).
viral infections (2 papers, 2024 to 2025). "However, genes such as Ifitm10, Ifi203, Ifi205, Ifit1 and Ifit2 showed an upregulated transcription at 6 and 24 h, suggesting that expression of some antiviral genes is regulated by alternative pathways to ensure host-cell survival during viral infections." (PMID 39296294, 2024).
neuroblastoma (1 paper, 2022). Neuroblastoma (NB) is the most common solid, extracranial childhood tumor. "The IFITM family (in humans, five IFITM members: IFITM1, IFITM2, IFITM3, IFITM5, and IFITM10; in mice, seven Ifitm members: IFITM1, IFITM2, IFITM3, IFITM5, IFITM6, IFITM7, IFITM10) was first discovered as interferon-induced genes in human neuroblastoma cells." (PMID 36012150, 2022).
osteogenesis imperfecta type 5 (1 paper, 2022). Osteogenesis imperfecta type V is a moderate type of osteogenesis imperfecta (OI), a genetic disorder characterized by increased bone fragility, low bone mass and susceptibility to bone fractures with variable severity. "The A subfamily is composed of the IFN-inducible and antiviral IFITM1, 2 and 3, as well as of IFITM5 and IFITM10, which are not IFN regulated and that in the case of IFITM5 are associated to Osteogenesis imperfecta type V, a bone-related genetic disease." (PMID 35396335, 2022).
cancer (2 papers, 2018 to 2020). A tumor composed of atypical neoplastic, often pleomorphic cells that invade other tissues. "Three DEG were also statistically significant after FDR correction: Npc1 in cellular processes and Ifitm10 and Sox17 in genes involved in cancer." (PMID 29950665, 2018).
tumor (2 papers, 2018 to 2020). "Pairs involving regulation of MARCO, IFITM10, and CD34 appear to function in HCC through changes involving tumor microenvironment and inflammation." (PMID 32228601, 2020).
IFITM10 also shares sentences with these, for which no sentence is quoted: breast carcinoma (4 papers); breast adenocarcinoma (1); bronchitis (1); colorectal cancer (1); entropion (1); hepatocellular carcinoma (1); immune deficiency (1); influenza (1); kidney adenocarcinoma (1); lung carcinoma (1); pneumonia (1).